HMGB1 (high mobility group box 1)
Diseases named in the same sentence as HMGB1 in open-access papers (continued):
Sharing a sentence is not in itself a finding about the gene and the disease.
autoimmune disease (113 papers, 2011 to 2025). A disorder resulting from loss of function or tissue destruction of an organ or multiple organs, arising from humoral or cellular immune responses of the individual to their own tissue constituents. "Systemic lupus erythematosus (SLE), an autoimmune disease closely associated with HMGB1 and TLRs, is characterized by autoantibody production and systemic inflammation involving multiple organ systems." (PMID 37667233, 2023). "HMGB1 is recognized as a damage-associated molecular pattern and expresses highly in autoimmune diseases, tissue injury, and infection." (PMID 37575469, 2023). "High mobility group box 1 (HMGB1) has been implicated as a pro-inflammatory protein in the pathogenesis of various inflammatory and autoimmune diseases, previous studies have identified the relevance of HMGB1 to inflammatory skin diseases." (PMID 36344541, 2022). "The diagnostic efficiencies of serum HMGB1 and anti-HMGB1 antibodies in differentiating the infectious disease subgroup from the autoimmune disease subgroup was assessed with ROC curve analysis." (PMID 33658546, 2021). "As an alarm, extracellular HMGB1 is a damage-associated molecular pattern (DAMP) which is involved in the pathogenesis of various autoimmune diseases as well as inflammatory diseases." (PMID 33658546, 2021). "Recent studies have highlighted a close association between high mobility group box 1 (HMGB1), chronic inflammation, and autoimmune diseases." (PMID 29410969, 2017). "Recent studies have highlighted a close association between HMGB1, chronic inflammation, and autoimmune diseases." (PMID 29410969, 2017). "High Mobility Group Box1 (HMGB1), a damage-associated inflammatory factor, plays an important role in the pathogenesis of numerous chronic inflammatory and autoimmune diseases." (PMID 27579314, 2016). "Proinflammatory and immune-stimulatory function of HMGB1 indicate its association with autoimmune diseases including rheumatoid arthritis and SLE." (PMID 26078984, 2015). "High mobility group box 1 (HMGB1), originally identified as a nuclear DNA binding protein, is a cytokine-like protein mediator implicated in infection, sterile injury, autoimmune disease, and IBD." (PMID 25127031, 2014). "HMGB1 protein has been detected in the active lesions of MS and elevated plasma HMGB1 levels are associated with disease activity in systemic lupus erythematosus and other autoimmune diseases." (PMID 23626809, 2013). "Based on these, it is inferred that HMGB1 may also cause an autoimmune response, produce autoantibodies, and cause autoimmune diseases." (PMID 35411013, 2022). "Furthermore, recent observations demonstrate a close association between high mobility group box 1 (HMGB1), chronic inflammation, and autoimmune diseases." (PMID 35558368, 2022). "Since then, the inflammatory role of HMGB1 has been demonstrated in multiple infectious contexts as well as in sterile injury such as liver ischemia/reperfusion and autoimmune diseases, establishing HMGB1 as a prototypical host-derived damage-associated molecular pattern (DAMP)." (PMID 34685561, 2021). "Recent studies have shown associations between HMGB1 and autoimmune diseases." (PMID 30338917, 2018). "Furthermore, in animal models of rheumatoid arthritis, anti-HMGB1 agents confer significant protection against joint tissue edema, supporting a pathogenic role for HMGB1 in autoimmune diseases." (PMID 25821489, 2015). "Rheumatoid arthritis(RA) is a common autoimmune disease associated with Th17 cells, but what about the effect of high-mobility group box chromosomal protein 1 (HMGB1) and the relationship between Th17-associated factors and HMGB1 in RA remains unknown." (PMID 22110531, 2012). "HMGB1 and Toll-like receptors are important biomarkers and potential therapeutic targets for autoimmune diseases." (PMID 40083379, 2025).
autoimmune disease (continued). "Understanding the role of the HMGB1/NLRP3 signaling pathway is especially pertinent for systemic diseases such as autoimmune disorders, cardiovascular conditions, and neurodegenerative diseases." (PMID 40688353, 2025). "Recently, numerous studies have revealed that HMGB1 is a potential therapeutic target in several autoimmune diseases." (PMID 40308590, 2025). "Increasing numbers of studies have identified HMGB1 as an activity biomarker in various autoimmune diseases, including multiple sclerosis, rheumatoid arthritis, inflammatory bowel disease, systemic lupus erythematosus and vitiligo." (PMID 40308590, 2025). "In the field of autoimmune diseases, anti-HMGB1 antibodies have demonstrated efficacy in animal models such as rheumatoid arthritis." (PMID 41296391, 2025). "The regulatory effect of HMGB1 on IL‐17A expression and function has been reported in some inflammatory and autoimmune diseases by the HMGB1‐Toll‐like receptor 4 (TLR4)‐interleukin (IL)‐23‐IL‐17A pathway." (PMID 38414294, 2024). "The binding of extracellular HMGB1 to Toll-like receptors (TLRs), such as TLR2 and TLR4 transforms HMGB1 into a pro-inflammatory cytokine, contributing to the occurrence and development of autoimmune diseases." (PMID 37667233, 2023). "The expression levels of HMGB1 and some TLRs are upregulated in tissues of patients with autoimmune diseases and animal models of autoimmune diseases." (PMID 37667233, 2023). "High mobility group box 1 (HMGB1) has proinflammatory effects and an immune-stimulatory function and plays a role in the pathogenesis of inflammatory and autoimmune diseases such as SLE." (PMID 37511964, 2023). "Extracellular HMGB1 has the ability to function as an autoantigen and induce the production of autoantibodies against the protein in both autoimmune diseases and healthy subjects." (PMID 37365509, 2023). "In particular, HMGB1 is involved in different autoimmune diseases, such as systemic lupus erythematous (SLE), idiopathic inflammatory myopathies, and rheumatoid arthritis." (PMID 37569519, 2023). "Previous studies have reported that HMGB1 functions as an important inflammatory cytokine in various autoimmune diseases." (PMID 37667233, 2023). "This review summarized the structural, functional, and immunological characteristics of HMGB1 and TLRs and the key roles of HMGB1 and TLRs in development of autoimmune diseases." (PMID 37667233, 2023). "Additional players in the pathogenesis of inflammatory and autoimmune diseases that were downregulated were the high-mobility group box 1 (HMGB1) and p38 mitogen-activated protein kinases (MAPK) signaling." (PMID 37999377, 2023). "HMGB1 has been demonstrated to play an essential role in autoimmune diseases such as rheumatoid arthritis (RA), as well as in inflammatory events." (PMID 37324499, 2023). "The role of HMGB1 in mediating the immune response has been established in several inflammatory and autoimmune diseases." (PMID 36551259, 2022). "The interference was pronounced in diseases with a high prevalence of autoantibodies against HMGB1, such as in patients with autoimmune diseases (and refs. therein)." (PMID 35454134, 2022). "The increased levels of HMGB1 in serum/plasma were observed in numerous inflammation-driven human diseases, such as autoimmune disorders (rheumatoid arthritis, systemic lupus erythematosus (SLE), and vessel vasculitis) and cancer." (PMID 35454134, 2022). "Because of its potential povital function, increasing research has been paid to the role of HMGB1 in inflammation and autoimmune diseases." (PMID 35250993, 2022). "HMGB1 plays its role in several autoimmune diseases such as encephalomyelitis, thyroiditis, myocarditis, systemic lupus erythematosus and many others." (PMID 35053208, 2021). "Current evidences point out that HMGB1 protein is involved in numerous chronic inflammatory and autoimmune diseases including rheumatoid arthritis, atherosclerosis, and systemic lupus erythematosus (SLE)." (PMID 33776579, 2021).
autoimmune disease (continued). "Because Th17 cells are involved in the induction of certain autoimmune diseases and Tregs in suppressing such disorders, our studies suggest several key molecules such as miR-132 and HMGB1 as potential targets to treat such inflammatory disorders." (PMID 33679792, 2021). "The relationship between HMGB1 and diseases has attracted widespread attention, including acute injury-related inflammatory responses, tumors, organ transplants, and autoimmune diseases." (PMID 35003098, 2021). "The concentrations of HMGB1 in the infectious disease subgroup and autoimmune disease subgroup were higher than those in the malignant tumor subgroup, undetermined subgroup, and healthy control group." (PMID 33658546, 2021). "Previous studies have demonstrated that levels of HMGB1 in serum were increased in patients with autoimmune diseases and correlated with disease activity." (PMID 34247641, 2021). "Extracellular HMGB1 is a proinflammatory mediator that participates in many inflammatory and autoimmune diseases." (PMID 34970076, 2021). "The serum concentration of HMGB1 in the infectious disease subgroup and autoimmune disease subgroup were significantly higher than that of healthy control group." (PMID 33658546, 2021). "As HMGB1 is elevated in sera of SLE patients and levels of serum HMGB1 correlate with disease activity, HMGB1 is assumed to play a role in these autoimmune diseases." (PMID 33806091, 2021). "High mobility group box 1 (HMGB1) is a damage-associated molecular pattern (DAMPs) and high in autoimmune diseases, tissue injury and infection." (PMID 33807604, 2021). "We describe the tolerance mechanism of HMGB1 that provides potential therapeutics for autoimmune diseases." (PMID 33807604, 2021). "HMGB-1 has been extensively studied to understand the pathogenesis of inflammatory and autoimmune diseases including endometriosis." (PMID 33815277, 2021). "The serum concentration of anti-HMGB1 antibodies in the autoimmune disease subgroup was significantly elevated than those of the healthy controls and other subgroups." (PMID 33658546, 2021). "HMGB-1 is involved in a series of diseases including sepsis, ischemia-reperfusion injury, neurological conditions, cardiovascular diseases, autoimmune diseases, endometriosis, and cancers." (PMID 33815277, 2021). "In-house built Anti-HMGB1 antibodies ELISA was first used for the detection of anti-HMGB1 antibodies in three common autoimmune diseases, i.e., SLE, SS, and RA, and healthy controls." (PMID 33658546, 2021). "The concentration of anti-HMGB1 antibodies in autoimmune disease subtype group was higher than those in other subgroups as well as healthy control group." (PMID 33658546, 2021). "Higher serum levels of HMGB1 were also found in several other autoimmune diseases, such as neuromyelitis optica, lupus nephritis, or rheumatoid arthritis." (PMID 32377165, 2020). "It has been proven in our previous study that HMGB1 is involved in the pathogenesis of inflammatory and autoimmune disorders, such as, Henoch– Schonlein purpura (HSP), allergic vasculitis (AV), and urticarial vasculitis (UV)." (PMID 33133061, 2020). "Thus, it is of extreme importance to further elucidate underlying mechanisms involving HMGB1 signaling in pathology, in order to possibly one day use it as a therapeutic target, prognostic or even diagnostic biomarker in patients suffering from autoimmune disorders and cancer." (PMID 31379812, 2019). "Increased serum and/or plasma levels of HMGB1 have been reported in autoimmune diseases such as systemic lupus erythematosus (SLE)." (PMID 30766892, 2019). "HMGB1 is upregulated in the serum/plasma of patients with various autoimmune disorders including vessel vasculitis, systemic lupus erythematosus (SLE) and rheumatoid arthritis (RA)." (PMID 31379812, 2019).
autoimmune disease (continued). "Previously, MP from patients with autoimmune diseases were reported to contain alarmins and other TLRs ligands, such as HMGB1, citrullinated peptides (CPs), nucleic acids, and chromatin." (PMID 31555283, 2019). "There is accumulating evidence that High Mobility Group Box 1 (HMGB1), an endogenous danger signal released when immune cells are activated or cell death occurs, contributes to the pathogenesis of inflammatory and autoimmune diseases, especially SLE." (PMID 30923525, 2019). "There is accumulating evidence that HMGB1 contributes to the pathogenesis of inflammatory and autoimmune diseases, especially SLE." (PMID 30923525, 2019). "First discovered in 1973, HMGB1 is presumably released from dead cells and secreted by inflammatory cells, and HMGB1 plays central roles in various disease states, including autoimmune disease, ischemia reperfusion injury, inflammation, and cancer." (PMID 29651425, 2018). "The relationship of HMGB1 with other autoimmune diseases, such as rheumatoid arthritis (RA), has also been suggested." (PMID 28649578, 2017). "HMGB-1 has been shown to play a key role in the pathogenesis of inflammatory and autoimmune diseases in humans." (PMID 28363279, 2017). "Many studies have demonstrated elevated circulating levels of high-mobility group box 1 (HMGB1) and decreased circulating levels of soluble receptor for advanced glycation end products (sRAGE) in patients with autoimmune diseases." (PMID 28558055, 2017). "Many studies have demonstrated elevated circulating levels of HMGB1 and decreased circulating levels of sRAGE in patients with autoimmune diseases such as rheumatoid arthritis (RA), systemic lupus erythematosus (SLE) and adult onset Still’s disease." (PMID 28558055, 2017). "Studies have demonstrated elevated circulating levels of HMGB1 and decreased circulating levels of sRAGE in autoimmune diseases." (PMID 28558055, 2017). "HMGB1 can contribute to progression of numerous chronic inflammatory and autoimmune diseases which is mediated in part by interaction with the receptor for advanced glycation endproducts (RAGE)." (PMID 26921471, 2016). "It was reported that HMGB1 is involved in a few autoimmune diseases such as RA, SLE and idiopathic inflammatory myopathies (IIM)." (PMID 27537498, 2016). "Increased serum and/or plasma levels of HMGB1 have been reported in several human autoimmune diseases such as systemic lupus erythematosus (SLE) and rheumatoid arthritis, indicating the involvement of HMGB1 in the pathogenesis of these autoimmune diseases." (PMID 27537498, 2016). "Thus, RAGE and HMGB1 are involved in the (patho-)physiology of thymus, as evidenced by differentiated thymic and systemic expression patterns that may act as diagnostic or therapeutic targets in autoimmune disease and cancer." (PMID 24705787, 2014). "Dysregulation of immunity in patients with MG, the close association of thymic abnormalities (including TETs) and MG, and the involvement of RAGE and HMGB1 in different cancers and autoimmune diseases sparked our interest in TETs, TH and thymic physiology." (PMID 24705787, 2014). "HMGB1 secreted into extracellular milieu is involved in many inflammatory, autoimmune diseases and cardiovascular disease by binding with its receptors." (PMID 24912759, 2014). "On the other hand, plasma cells release HMGB1 into the extracellular milieu following LPS-stimulated maturation, demonstrating its pro-inflammatory effects in promoting autoimmune disease and chronic inflammation." (PMID 23519706, 2013). "In summary, HMGB1 is a powerful danger signal that plays a complex role in the pathogenesis of autoimmune diseases." (PMID 23772226, 2013). "It has been recognized that HMGB1 plays an important role in autoimmunity disease and cancers, and HMGB1, TLR4 and NF-κB have all been shown to participate in the progression and metastasis of malignant tumors." (PMID 23803172, 2013).
autoimmune disease (continued). "HMGB1 also played important roles in other autoimmune diseases as well as in acute allograft rejection." (PMID 22110531, 2012). "Elevated serum levels of HMGB1 have been detected in autoimmune diseases including Systemic lupus erythematosus (SLE)." (PMID 22348591, 2012). "Increased expression of HMGB1 has also been reported in other autoimmune diseases particularly in RA." (PMID 21548924, 2011). "Recent studies showed increased levels of serum HMGB1 and anti-HMGB1 in several autoimmune diseases including SLE." (PMID 21548924, 2011). "Thus, HMGB1 is an indispensable biomarker and an important therapeutic target for autoimmune diseases." (PMID 40308590, 2025). "Moreover, PEDV-N has been shown to promote the acetylation and release of high mobility group box 1 (HMGB1), a key proinflammatory factor implicated in the pathogenesis of various inflammatory and autoimmune diseases." (PMID 40002953, 2025). "Additionally, the inhibition of HMGB1 expression or its activity has beneficial effects on disease activity in animal models of autoimmune diseases." (PMID 40308590, 2025). "HMGB1 is reportedly upregulated and is a critical biomarker for monitoring disease activity in several chronic inflammatory or autoimmune disorders, including multiple sclerosis, rheumatoid arthritis, inflammatory bowel disease, systemic lupus erythematosus and vitiligo." (PMID 40308590, 2025). "Thus, HMGB1 and TLRs are indispensable biomarkers and important therapeutic targets for autoimmune diseases." (PMID 37667233, 2023). "Additionally, recent advances in establishing HMGB1 and TLRs as therapeutic targets for autoimmune diseases have been discussed." (PMID 37667233, 2023). "Rheumatoid Arthritis (RA) is an autoimmune disease that is closely related to HMGB1." (PMID 37667233, 2023). "As a non-histone chromatin-associated protein, HMGB1 performs a pivotal function in various human diseases, including autoimmune diseases, neurodegenerative diseases and cancer." (PMID 37932766, 2023). "According to other literatures and our preliminary researches, the high mobility group box 1 (HMGB1) played a key role in inflammation-related immune regulation, and other studies have shown that anti-HMGB1 autoantibody can be detected in a variety of autoimmune diseases." (PMID 35411013, 2022). "HMGB1 is an alarmin, whose circulating levels may be elevated during chronic inflammation, autoimmune diseases, or after surgical/anesthesia trauma." (PMID 35558368, 2022). "Furthermore, HMGB1 is closely related to sterile inflammation and can promote autoimmune diseases as an endogenous adjuvant." (PMID 35250993, 2022). "HMGB1 is well-established in driving inflammatory and autoimmune diseases." (PMID 36551259, 2022). "Interestingly, it has been investigated that HMGB1 is likely to be involved in the development of autoimmune diseases such as systemic lupus erythematosus and rheumatoid arthritis." (PMID 34247641, 2021). "It has been found that RAGE interacts with HMGB1 to activate dendritic cells and B cells, which may lead to autoimmune diseases by changing antigen presentation to T cells and other suitable effector cells." (PMID 34620045, 2021). "In recent years, many studies, including our previous studies, have indicated that HMGB1 is closely related to the pathogenesis of chronic inflammatory diseases (e.g., tuberculous meningitis) and autoimmune diseases [especially systemic lupus erythematosus (SLE), rheumatoid arthritis, etc.]7–9." (PMID 33658546, 2021). "Extracellular HMGB1 acts as an alarmin in multiple autoimmune diseases." (PMID 33391251, 2020). "Defects in NET degradation have also been associated with other autoimmune disorders characterized by the presence of autoantibodies but the role of HMGB1 in these settings has not been thoroughly explored." (PMID 31379812, 2019).